SRSF1 (serine and arginine rich splicing factor 1)
Diseases named in the same sentence as SRSF1 in open-access papers (continued):
Sharing a sentence is not in itself a finding about the gene and the disease.
cancer (continued). "Interestingly, some SRSF1 translational targets, including NDC80 and centrosomal proteins, have been previously identified in an siRNA screen looking for proteins involved in centrosome clustering in cancer cells." (PMID 24842991, 2014). "Thus, the altered expression of SRSF1 and SRSF6 in many types of tumors could impact malignant transformation by ensuring the proper balance of pro- and anti-angiogenic isoforms in cancer cells." (PMID 24285959, 2013). "In addition, SRSF1 could also control the splicing of many apoptotic genes, such as MCL, BIM, and Bcl-x to regulate apoptosis in cancers." (PMID 31065692, 2019). "Interestingly, SRSF1 is known to regulate a plethora of biological functions, further to splicing, within cells and is located in the middle of a self-regulatory network involving several splicing factors such as PTBP1 and SRSF3 that act as known oncoproteins in different types of cancer." (PMID 29415469, 2018). "This may suggest that SRSF1 is not the key driver of cancer metastasis in SCLC." (PMID 27093186, 2016). "To decipher the cancer-promoting mechanisms of SRSF1, we examined changes in gene expression in human U2OS cells under conditions with and without SRSF1 knockdown." (PMID 38735973, 2024). "For example, SRSF1 and SRSF2 presented relatively higher CNV amplification in the vast majority of cancer types, with the lack of deep deletion." (PMID 38015716, 2023). "In low USP15 and USP4 upon depletion, SRSF1 is down-regulated with substantial retention of the C-terminal intron sequences recognized as an altered isoform SRSF1-3, which is degraded by NMD and thus do not show any effects on cancer cell phenotype." (PMID 35027535, 2022). "After RNAi-mediated knockdown of hnRNP A1 we did not detect any variation in the level of SRSF1 and hnRNP H. Interestingly, however, we observed upregulation of hnRNP A2/B1, a factor known to regulate the EMT program and frequently overexpressed in cancer." (PMID 23863836, 2013).
tumor (149 papers, 2005 to 2026). "Among the SRSF1-downregulated DEGs, those linked to tumor-related functions were primarily involved in glycolytic metabolism, the HIF1a signaling pathway, and metabolic pathways, rather than the upregulated genes." (PMID 39837814, 2025). "An intriguing finding emerged when SRSF1-deficient tumor cells were introduced into various mouse strains: while SRSF1 knockdown slightly hinders Hep1-6-OVA tumor growth in nude mice, the effect is significantly greater in immunocompetent C57BL/6 mice." (PMID 39837814, 2025). "This suggests that SRSF1 promotes SCLC malignant progression by regulating gene splicing associated with tumor growth, invasion and metastasis." (PMID 40129567, 2025). "Similar results showed that glycolytic genes cannot be rescued by overexpression of SRSF1 mutated protein in shSRSF1 tumor cells." (PMID 39837814, 2025). "Experimental knockdown of SRSF1 or the RPS6KB1 splice variant induced by SRSF1 in a NSCLC cell line with high SRSF1 expression inhibited colony formation in vitro; and the former also inhibited xenograft tumor growth in vivo." (PMID 34065983, 2021). "AS regulated by SRSF1 generates protein variants involved in cell migration, epithelial to mesenchymal transition, oncogenic activation, loss of tumor suppressor activity and angiogenesis." (PMID 33287867, 2020). "For example, the expression of the Serine/Arginine-Rich Splicing Factor 1 (SRSF1) is increased in several tumor types, and fibroblasts overexpressing SRSF1 can cause tumors when injected into mice." (PMID 28493890, 2017). "For instance, the Serine/Arginine-Rich Splicing Factor 1 (SRSF1) was found to be over-expressed in several tumor types, and fibroblasts overexpressing SRSF1 caused tumor formation when injected into mice." (PMID 27598998, 2016). "Importantly, SRSF1 overexpression was linked with shorter survival in two independent MM datasets and was correlated with the number of AS events, impacting tumor cell proliferation." (PMID 36535935, 2022). "An increasing number of mutations at core spliceosome components, such as S3FB1 and U2AF1, or upregulation of specific splicing factors, such as SRSF1 and other members of the SR protein family, which are now considered oncogenes, have been intimately linked to tumour progression and malignancy." (PMID 33845831, 2021). "In addition, the expression SRSF1 has been shown to be increased in several tumor types and fibroblasts overexpressing SRSF1 caused tumor formation when injected into mice." (PMID 27565572, 2016). "It remains to be established whether tumor cells can release signals that induce increased SRSF1 expression in tumor-associated fibroblasts." (PMID 26273603, 2015). "The effect of the RBM15/m6A/SRSF1/ATP7B axis on tumor growth was evaluated using tumor xenografts in nude mice." (PMID 40923717, 2026). "SRSF1-sh tumor cells exhibited strong signals for both IFN-γ and GZMB, in contrast to control tumors, which produced minimal amounts of these cytokines." (PMID 39837814, 2025). "From the TCGA database and GTEx database, we found that SRSF1 mRNA expression was significantly upregulated in 15 of 31 types of tumor tissues." (PMID 39837814, 2025). "The heatmap result showed that glycolysis related genes were also downregulated when SRSF1 was silenced in tumor cells." (PMID 39837814, 2025). "We therefore introduce a paradigm targeting SRSF1 that simultaneously disrupts tumor cell metabolism and enhances the antitumor immunity of CD8+ T cells." (PMID 39837814, 2025). "We investigated if deleting SRSF1 enhances the tumor-specific activity of transgenic OT-I CD8 + T cells transferred into mice with OVA-expressing tumors." (PMID 39837814, 2025). "Specifically, the inactivation of SRSF1 in tumor cells leads to a reduction in glycolytic metabolism and results in a marked increase in the number of tumor-infiltrating CD8+ T cells, along with a decrease in regulatory T cells (Tregs) within the TME." (PMID 39837814, 2025).
tumor (continued). "LncRNA H19 can also competitively bind to miR-107, releasing YTHDC1 mRNA and interacting with YTHDC1 protein to modulate SRSF1 stability, eventually influencing IL-6 and IL-10 AS and driving tumor growth." (PMID 40032844, 2025). "Transcriptome analysis revealed significant changes in co-cultured CD8+ T cells due to SRSF1-sh in tumor cells." (PMID 39837814, 2025). "Small molecule inhibitors targeting SRSF1 have already demonstrated the effect of enhancing the anti-tumor immune response in animal models." (PMID 40537877, 2025). "When compared to control CD8 + T cells, RNA-seq analysis of SRSF1-knockout (KO) cells revealed that SRSF1 inactivation increased glycolytic metabolism, which is known to enhance T cell-mediated tumor immunity." (PMID 39837814, 2025). "SRSF1 depletion suppresses glycolytic genes in tumor cells by limiting bZIP and MYC transcription factors, thereby eliminating the metabolic barrier to T cell activation." (PMID 39837814, 2025). "We have demonstrated that CD8 T cells and tumor cells respond differently metabolically to SRSF1 suppression." (PMID 39837814, 2025). "Future research can be directed towards patient cohorts to help ascertain the correlation between the expression levels of SRSF1 and clinical outcomes, such as tumor grade, Ki-67 expression, and prognosis." (PMID 40176901, 2025). "We noted a marked increase in CD8+ T cell infiltration within tumor tissues of SRSF1-sh Hep1-6-OVA tumors." (PMID 39837814, 2025). "GSEA of CD8+ T cell effector signature genes consistently showed that T cells co-cultured with SRSF1-sh tumor cells were in a more cytotoxic state compared to those co-cultured with control cells." (PMID 39837814, 2025). "Depleting SRSF1 in tumor cells reduced glycolytic metabolism and activated CD8+ T cells by limiting abnormal alternative splicing of transcription factors and genes related to glycolysis." (PMID 39837814, 2025). "Inactivating SRSF1 in CD8+ T cells preserve a substantial pool of cytotoxic CD8+T cells that possess improved anti-tumor activity." (PMID 39837814, 2025). "The inactivation of SRSF1 in tumor cells reduces transcription factors, including c-Jun, c-myc, and JunB, facilitating glycolytic metabolism reprogramming, which restores CD8+ T cell function and inhibits tumor growth." (PMID 39837814, 2025). "EBNA1 interacts with the splicing factor SRSF1 to regulate the expression of the SRRM1 splicing isoforms, thereby promoting EBV‐associated tumor development." (PMID 40729735, 2025). "The study findings suggest that PC exhibits heterogeneous protein expression patterns, with SRSF-1 expression playing a significant role in tumor aggressiveness and prognosis." (PMID 38731981, 2024). "We have previously shown that on PC patients, positive SRSF-1 expression was associated with AR, Ki-67, IR-α, and microvascular density, indicating a potential role of SRSF-1 in driving tumor aggressiveness." (PMID 38731981, 2024). "As for SRSF1, it has been primarily studied for promoting tumor progression via alternatively splicing RNA as a splicing factor or for its role in binding to ncRNA to regulate the transcription of other molecules." (PMID 38735973, 2024). "Subsequently, circCMTM3/STAT5A/SRSF1 positive feedback loop sustainably enhances VM formation and accelerates tumor progression in GBM." (PMID 39310105, 2024). "It has been reported that SRSF1 is highly expressed in multiple tumor tissues, and similarly, SRSF1 is upregulated in HCC tumor tissues." (PMID 36670110, 2023). "As expected, the SRSFs with CNV amplification displayed significantly higher expression in tumor tissues compared to normal ones (e.g., SRSF1, SRSF2, SRSF3, and SRSF6)." (PMID 38015716, 2023). "We showed that GSCAR interacted with miR-6760-5p to increase the expression of the oncoprotein SRSF1, leading to increased tumor growth and migration in U251 and A172 cells." (PMID 37063420, 2023).
tumor (continued). "Srsf1 has emerged as a key oncodriver in tumor progression such as gliomagenesis for its role in alternative splicing." (PMID 36831877, 2023). "The dependency score of SRSF1 is −1.113, which means that SRSF1 is a common essential gene for tumor cell lines." (PMID 37206090, 2023). "HLTF plays a tumor-promoting role by activating the ERK/MAPK signaling pathway by increasing SRSF1 protein stability." (PMID 36670110, 2023). "Our results reveal that the GSCAR/miR-6760-5p/SRSF1 axis is important for tumor growth, while the GSCAR/DHX9-IGF2BP2/Sox2 feedback loop is critical for GSC maintenance and TMZ resistance." (PMID 37063420, 2023). "Together, these data suggest that RNA splicing, and SRSF1 in particular, control the plasticity of tumour cells and is a viable therapeutic target in CRC." (PMID 35589755, 2022). "Our study, for the first time, demonstrated the biological function of SRSF1 in ovarian follicles and proved its apoptosis-resistant effect in non-tumor tissue." (PMID 35163432, 2022). "On the contrary, increasing SRPK1 in tumor phosphorylates SRSF1 and stimulates its nuclear import, which favors the splicing at the proximal splice site of VEGF pre-mRNA and leads to the expression of the VEGFxxx isoform and neovascularization." (PMID 36140826, 2022). "Our observation of E2F control of SRSF1 expression highlights the concept that splicing programs and transcriptional programs participate in the corruption of cellular processes during tumor initiation and progression." (PMID 36535935, 2022). "Collectively, these results indicate that RBM4-S functions as a tumor promoter by abolishing RBM4-FL-mediated inhibition of SRSF1-mTORC1 signaling pathway activity." (PMID 35361747, 2022). "We show that the splicing factor SRSF1 controls the plasticity of tumour cells by controlling Kras splicing and is required for CRC invasion in a mouse model of carcinogenesis." (PMID 35589755, 2022). "BIN1 is a well-recognized tumor suppressor among the SRSF1 target genes, which is lost in several NSCLC, and restored expression of BIN1 can suppress malignant phenotypes." (PMID 35027535, 2022). "RBM4-S functions as a tumor promoter by abolishing RBM4-FL-mediated inhibition of the activity of the SRSF1-mTORC1 signaling pathway." (PMID 35361747, 2022). "Protein kinase A (PKA), a novel tumor biomarker, phosphorylates SRSF1 at serine 119 in the RRM, which enhances the RNA-binding properties of SRSF1, and increases SRSF1′s activity in regulating the Minx transcript splicing in vitro." (PMID 36140826, 2022). "IHC analysis results revealed that circ_000829 overexpression reduced Ki-67 positive cells in tumor tissues, and that overexpression of circ_000829 diminished the expression of SRSF1 and UBE2C (proliferation- and invasion-related marker) in the tumor tissues." (PMID 36062189, 2022). "Our results suggested that inhibiting the expression of MALAT1 or SRSF1 significantly slowed tumor formation in addition to reducing the size of the formed tumors (p < 0.05)." (PMID 34001131, 2021). "Further study showed that the tumor-promoting role of SRSF1 can be significantly attenuated by silencing TNPO3, confirming that only nucleus SRSF1 exerts pro-oncogenic effects." (PMID 33602301, 2021). "Compared with the control group, tumor volumes were decreased in the circATP5B knockdown group, the miR-185-5p mimic group, and the SRSF1 overexpression combined with circATP5B knockdown group." (PMID 33858489, 2021). "Immunohistochemistry was performed to detect the effects of the SRSF1/circATP5B/miR-185-5p/HOXB5 axis on tumor tissues." (PMID 33858489, 2021). "The expression of SRSF1 is related to the occurrence, development and treatment response of tumor, and SRSF1 is highly expressed in tumor cells." (PMID 34011971, 2021). "Silencing SRSF1 decreased tumor growth in vivo and this led to an increased overall survival in mice." (PMID 34065983, 2021).
tumor (continued). "On the 16th day post inoculation, our results demonstrated that depletion of MALAT1 or SRSF1 further reduced the tumor volume while upregulation of MALAT1 markedly increased the tumor size (p < 0.05)." (PMID 34001131, 2021). "SRSF1 is a prototypical member of the SR family and a proto-oncogene, whose expression levels are increased in different tumor types probably as a consequence of gene amplification." (PMID 33918758, 2021). "Nevertheless, the pivotal SRSF1-driven AS landscape responsible for oncogenesis usually differs largely in distinct tumor types." (PMID 33992102, 2021). "Data obtained from public databases and clinical samples confirmed that SRSF1 was upregulated in BRCA, and positively associated with tumor grade and the Ki-67 index." (PMID 33992102, 2021). "In vivo analysis confirmed that knockdown of SRSF1 significantly inhibited tumorigenesis, as measured by tumor size." (PMID 33992102, 2021). "Based on the analysis results from public datasets, we further explored the SRSF1 expression difference in tumor and adjacent tissues." (PMID 33992102, 2021). "Experimental overexpression of SRSF1 in mouse fibroblasts increased anchorage-independent colony growth in vitro and tumor growth in nude mice in vivo; and protected adenovirus E1A-transformed mouse embryo fibroblasts against apoptosis." (PMID 34065983, 2021). "Collectively, our data confirmed that SRSF1 facilitates oncogenesis by regulating the AS of tumor-related genes, highlighting the significance of AS as a pivotal regulator of tumorigenesis." (PMID 33992102, 2021). "A series of studies found that dysregulated expression of SRSF1 protein can also alter alternative splicing of many other tumor-related genes." (PMID 32760211, 2020). "We show that, in tumor endothelium, Wt1, Srpk1, and Srsf1 are upregulated compared to normal lung endothelium." (PMID 30641926, 2019). "We show here that Wt1, Srpk1, Srsf1, and the angiogenic Vegf 164a isoform are highly expressed in tumor endothelial cells compared to normal lung endothelium." (PMID 30641926, 2019). "Wt1, Srpk1, Srsf1, and the angiogenic VEGF164a isoform were highly expressed in tumor endothelium compared to normal lung endothelium." (PMID 30641926, 2019). "Highly augmented expression of SRSF1 by ~ 1.86 folds and hnRNPA2B1 by ~ 2.66 folds was noted in HepR21 cells which are in concurrence with the increased tumor potency in these cells compared to HepG2." (PMID 29535843, 2018). "It is also very imperative to mention here about our present observation, on the correlation of tumor potency of HepG2 cells by overexpressing HABP1 with the upregulation of oncogenic splicing factors SRSF1 and hnRNPA2B1." (PMID 29535843, 2018). "With regard to SRSF1, one study reported that phosphorylation of SRSF1 regulated alternative splicing of tumor-related Rac1b in CRC cells." (PMID 30155352, 2018). "Treatment of colon cancer cells with ibuprofen, for example, led to inhibition of tumor-related RAC1b and this involved reduced phosphorylation of SRSF1, which is required for inclusion of the alternative exon." (PMID 29286307, 2017). "In a complementary approach, we investigated upon the relevance of targeting the SRSF1 splicing factor or its binding sites and the slowing down of the tumor growth by favoring VEGFxxxb expression." (PMID 27999187, 2017). "SRSF1 overexpression was able to induce tumor formation in epithelial cells and inhibit apoptosis in breast cancer cells." (PMID 27613060, 2016). "We observed elevated SRSF1 levels in three of the four tumor samples compared to their corresponding normal tissue-matched controls." (PMID 25845590, 2015). "For instance, overexpression of SRSF1 in MCF-7 breast cell line has been linked to elevated levels of the isoforms BIN1 +12A and S6K1-p31 which are involved in decreased tumor suppressor activity and increased oncogenic activity, respectively." (PMID 26273588, 2015).